ZNF276 (zinc finger protein 276)
Description:
May be involved in transcriptional regulation.
Synonyms: CENP-Z; ZFP276; ZNF477; MGC45417; CENPZ; ZADT
Tractability: Antibody: the Human Protein Atlas places it where antibodies can reach. PROTAC: ubiquitination databases record sites on it; its protein half-life has been measured.
Gene: Protein-coding gene on chromosome 16 (89,720,400 to 89,740,925, forward strand). Ensembl gene ENSG00000158805.
Subcellular location: Nucleus; Chromosome, centromere, kinetochore
Subcellular location (Human Protein Atlas): Cytosol; Nucleoplasm; Nucleoli; Plasma membrane
Gene Ontology:
Molecular function: protein binding; sequence-specific double-stranded DNA binding; DNA-binding transcription activator activity, RNA polymerase II-specific; RNA polymerase II cis-regulatory region sequence-specific DNA binding; zinc ion binding
Biological process: regulation of transcription by RNA polymerase II; positive regulation of transcription by RNA polymerase II
Cellular component: kinetochore; nucleus
Genetic constraint (gnomAD): Loss-of-function variants: 61 observed, 65.27 expected, observed/expected ratio (o/e) 0.93, 90% interval 0.76 to 1.16. The synonymous counts are far from expectation, so gnomAD's model fits this gene poorly and the ratio says little. Missense variants: 1,084 observed, 841.96 expected, observed/expected ratio (o/e) 1.29, 90% interval 1.22 to 1.35. Synonymous variants: 496 observed, 339.02 expected, observed/expected ratio (o/e) 1.46, 90% interval 1.36 to 1.58.
Homologues: Orthologues: chimpanzee ZNF276 (99% identical), macaque ZNF276 (95% identical), guinea pig ZNF276 (83% identical), rat Zfp276 (81% identical), mouse Zfp276 (81% identical), pig ZNF276 (77% identical), dog ZNF276 (75% identical), rabbit ZNF276 (71% identical), tropical clawed frog znf276 (50% identical), zebrafish znf276 (41% identical). Paralogues in human: ZNF653 (21% identical), ZNF692 (19% identical), ZFP91 (19% identical), PRDM1 (16% identical), ZNF143 (12% identical), ZNF76 (12% identical), PRDM10 (12% identical), ZNF384 (12% identical), HIC1 (11% identical), ZNF410 (11% identical), PATZ1 (11% identical), ZBTB16 (11% identical), and 24 more.
Diseases named in the same sentence as ZNF276 in open-access papers:
ZNF276 is named in the same sentence as 7 diseases in open-access papers, as found by Europe PMC text mining. Sharing a sentence is not in itself a finding about the gene and the disease. The quoted sentences say what the papers report.
breast carcinoma (3 papers, 2022 to 2023). "Gain-of and loss-of function suggested that ZNF276 is essential for the proliferation, migration and invasion of breast cancer cells in vitro and metastasis in vivo." (PMID 36085146, 2022). "ZNF276 mutations have been identified in breast cancer and may also be involved in the progression of Fanconi anaemia." (PMID 36568422, 2022). "ZNF276 can promote the malignant phenotype of breast cancer by activating the CYP1B1-mediated Wnt/β-catenin pathway." (PMID 37143720, 2023). "The immunohistochemical score (H-score) showed that ZNF276 expression was significantly higher in breast cancer tissues than in adjacent tissues." (PMID 36085146, 2022). "Both survival analysis showed that higher expression of ZNF276 indicated a lower overall survival of breast cancer patients." (PMID 36085146, 2022). "In this study, we found that the protein expression of ZNF276 was upregulated in breast cancer tissues and cells." (PMID 36085146, 2022). "The subcellular localization of β-catenin affected by ZNF276 overexpression was detected in breast cancer cells using immunofluorescence." (PMID 36085146, 2022). "Our study shed light on the crucial role and mechanism of ZNF276 in the progression of breast cancer in mediating cell proliferation and metastasis." (PMID 36085146, 2022). "Collectively, these findings highlight the oncogenic role of ZNF276 on breast cancer cell proliferation and metastasis." (PMID 36085146, 2022). "In summary, this is the first study describing the expression of ZNF276 in breast cancer tissues and cells and elucidating a novel mechanism by which ZNF276 promotes cell proliferation, migration and invasion through activation of the Wnt/β-catenin pathway." (PMID 36085146, 2022). "Taken together, these results demonstrated that CYP1B1 is the functional target of ZNF276 in breast cancer." (PMID 36085146, 2022). "Overexpression of ZNF276 promoted, while silencing of ZNF276 inhibited, the proliferation, migration and invasion of breast cancer cells." (PMID 36085146, 2022). "Here, we show that zinc finger protein 276 (ZNF276) is highly expressed in breast cancer tissues and cell lines." (PMID 36085146, 2022). "The results showed that the mRNA and protein levels of ZNF276 were higher in breast cancer tissues than normal tissues." (PMID 36085146, 2022). "Overexpression of MAGEB2 significantly recovered the proliferation and migration abilities of breast cancer cell with ZNF276 silencing." (PMID 36085146, 2022). "Altogether, these results indicate that ZNF276 is highly expressed in breast cancer tissues and cell lines." (PMID 36085146, 2022). "In a word, ZNF276 could promote the proliferation, invasion and migration of breast cancer cells in vitro and in vivo." (PMID 36085146, 2022). "In this study, we found that ZNF276 was upregulated in both breast cancer tissues and cell lines." (PMID 36085146, 2022). "Targeting ZNF276/MAGEB2 axis may serve as a potential therapeutic strategy for breast cancer patients." (PMID 36085146, 2022). "As ZNF276 was overexpressed in breast cancer tissues and cells, we supposed that ZNF276 might play a role in breast cancer pathogenesis." (PMID 36085146, 2022). "We then hypothesized that CYP1B1 could be responsive for the effects of ZNF276 on the malignant phenotypes of breast cancer cells." (PMID 36085146, 2022). "We applied CUT&Tag for detection of ZNF276-DNA interaction status in breast cancer cells." (PMID 36085146, 2022). "Moreover, overexpression of ZNF276 accelerated cell proliferation, migration and invasion, indicating that ZNF276 functions as an oncogene in breast cancer." (PMID 36085146, 2022). "Further validation of ZNF276 protein expression using six breast cancer cells with different molecular subtypes indicated that compared with MCF-10A, the protein levels of ZNF276 were upregulated in most breast cancer cells, but ZNF276 was undetectable in SK-BR-3." (PMID 36085146, 2022).
breast carcinoma (continued). "We examined the expression of ZNF276 in 10 breast cancer tissues and paired normal tissues." (PMID 36085146, 2022). "Mutation analysis of its coding region suggested that ZNF276 might be a tumor suppressor, however, there is no as of yet definitive evidence on its role in breast cancer." (PMID 36085146, 2022). "ZNF276 recruits MAGEB2 to facilitate the transcription of CYP1B1 and the activation of the Wnt/β-catenin pathway, leading to a malignant breast cancer phenotype." (PMID 36085146, 2022). "The expression of ZNF276 was higher in Luminal A and HER2 breast cancer than that in other subtypes." (PMID 36085146, 2022). "The Cancer Cell Line Encyclopedia (CCLE) database showed that the mRNA level of ZNF276 was higher in Luminal positive and HER2 positive breast cancer cells." (PMID 36085146, 2022).
breast tumors (1 paper, 2022). "The coding gene of ZNF276 lies in chromosome 16q23.4 where loss of heterozygosity frequently occurs in breast tumors." (PMID 36085146, 2022). "Firstly, the RNA-seq data from the TCGA database showed that ZNF276 mRNA levels were significantly upregulated not only in breast tumors but also in colon, liver and gastric cancers compared to normal tissues." (PMID 36085146, 2022).
cancer (1 paper, 2022). A tumor composed of atypical neoplastic, often pleomorphic cells that invade other tissues. "ZNF276 is a member of ZNF family whose biological effect in various malignant tumors is largely unknown." (PMID 36085146, 2022). "Therefore, how ZNF276 functions in other cancers still requires exploration." (PMID 36085146, 2022).
tumor (1 paper, 2022). "Thirty days after the tumor cell injection, the tumor weight and volume in nude mice with ZNF276-stably expressing cells were significantly larger and grew faster than those in the control group." (PMID 36085146, 2022). "There was a significantly increased level of tumor cell proliferation marker Ki67 in the ZNF276 overexpression group than in the control group." (PMID 36085146, 2022).
ZNF276 also shares sentences with these, for which no sentence is quoted: Fanconi anaemia (2 papers); gastric cancer (1); Spastic paraplegia 7 (1).